SET (SET nuclear proto-oncogene)
Diseases named in the same sentence as SET in open-access papers (continued):
Sharing a sentence is not in itself a finding about the gene and the disease.
tumor (80 papers, 2006 to 2025). "Deleting the multifunctional protein SET inhibits tumor growth by suppressing migration to tumors of tumor-associated macrophages (TAMs), immune cells that have been turned against the body to promote tumor growth and block antitumor immune cells." (PMID 36224346, 2022). "In the transwell migration assay, OA significantly reversed the reduction in macrophage chemotaxis toward hypoxic tumor supernatant caused by SET deletion." (PMID 36224346, 2022). "Overexpression of SET has been reported in several solid tumors and hematological malignancies and SET expression has been functionally linked to poor prognosis, progression of the neoplastic disease and development of resistance to treatment." (PMID 36345878, 2022). "Additionally, SET also regulates the mobility and distribution of tumor-associated macrophages (TAMs) in tumor regions, providing an immunosuppressive environment." (PMID 39776803, 2025). "Interestingly, heterozygous deletion of Kmt2c-SET in combination with loss of Pten (Pten∆/∆Kmt2cSET∆/+) was sufficient to induce increased prostate weight indicative of tumour development." (PMID 35354467, 2022). "Furthermore, SET overexpression is associated with worse recurrence-free survival and it has been shown to reduce tamoxifen-induced anti-tumour effect in patients with primary breast cancer." (PMID 34244560, 2021). "DNA methylation profile of 24 tumour suppressors evidenced that SET accumulation decreased DNA methylation in association with loss of 5-methylcytidine, formation of 5-hydroxymethylcytosine and increased TET1 levels, indicating an active DNA demethylation mechanism." (PMID 28460463, 2017). "However, we currently can not exclude the possibility that these mesenchyme-associated proteins acquired by invasive tumor cells may be directly or indirectly regulated by miR-502-3p, HuR or SET." (PMID 31752906, 2019). "Protein phosphatase 2A (PP2A), a well-established tumor suppressor, is functionally impaired in gastric cancer due to the overexpression of endogenous inhibitors such as SET and CIP2A." (PMID 41220952, 2025). "For example, cytosolic SET primarily binds the catalytic subunit of serine/threonine-protein phosphatase 2 A (PP2A) and inhibits PP2A enzymatic activity and tumor suppressive actions, by which SET promotes cell proliferation, anti-apoptosis and metastasis." (PMID 38355937, 2024). "As a multifaceted protein, SET can be distributed in both the cytosol and nucleus and physically interact with diverse key factors to promote tumor-related behaviors of the cell." (PMID 38355937, 2024). "Intriguingly, SETBP1 interacts with RAS/MAPK cascade by inhibiting the activity of the tumor suppressor PROTEIN PHOSPHATASE 2A (PP2A), which regulates this pathway through the stabilization of SET, another important tumor suppressor." (PMID 38520002, 2024). "The fact that SET/TAF-Iβ is required for the establishment of silencing of target genes in various tumor cells raise questions about the contribution of SET/TAF-Iβ in transcriptional repression regulatory mechanisms independent of PRC1-mediated H2AK119ub." (PMID 37746636, 2023). "Lower TRIM4 and higher SET expression levels, respectively, were related to larger tumor size and lymph node metastasis, whereas they were unrelated to age, histological grade, HER‐2, PGR, or Ki‐67 expression." (PMID 35843886, 2022). "First, we examined the subcellular location of SET in macrophages in response to hypoxic tumor supernatant." (PMID 36224346, 2022). "Herein, we report that genetic deletion of SET significantly impairs macrophage entry into hypoxic tumor regions and potentiates antitumor immunity in a syngeneic mouse tumor model." (PMID 36224346, 2022). "While the tumours were predominantly luminal, they showed low predicted endocrine sensitivity by the SET gene signature." (PMID 36096872, 2022).
tumor (continued). "To investigate the role of myeloid SET in tumor immunity, we generated a mouse model with inducible myeloid SET ablation by crossbreeding LysM-Cre and SET fl/fl mice." (PMID 36224346, 2022). "Western blotting showed that hypoxic tumor supernatant significantly promoted the translocation of SET from the nucleus to the cytoplasm." (PMID 36224346, 2022). "They conclude that deletion of SET prevents TAMs from detecting signals from the tumor microenvironment, thereby decreasing TAM recruitment and suppressing tumor growth." (PMID 36224346, 2022). "We have previously reported the role of miR-199b promoting 5-FU response in a SET-dependent manner leading to the reactivation of the tumor suppressor PP2A." (PMID 34638487, 2021). "Lastly, our group has recently reported that miR-199b is a frequently downregulated tumor suppressor miRNA in LARC that directly targets the PP2A inhibitor SET Nuclear Proto-Oncogene (SET), which has been previously shown to be involved in 5-FU resistance." (PMID 32722203, 2020). "Accumulated evidence demonstrated that SET functions as an oncogene in several neoplasms and promotes tumorigenesis." (PMID 31097686, 2019). "Having demonstrated the role of mitotic phosphorylation of SET in cell culture models, we next evaluated the influence of SET and its mitotic phosphorylation on tumor growth in animals." (PMID 31097686, 2019). "The SET gene plays a key role in human acute undifferentiated leukemia by acting as a tumor promoter." (PMID 29467924, 2018). "Although there are four known isoforms of human SET, their individual roles in tumor development and progression remain obscure." (PMID 28978088, 2017). "We selected the HN12 cell line – which exhibited the most marked change in average DNA methylation after SET knockdown – and the non-tumour cell line HEK293 for the assay." (PMID 28460463, 2017). "We propose HDAC inhibitors as potential pharmacological agents to recovery gene expression in SET-accumulating tumours." (PMID 28460463, 2017). "Altogether, these data indicated that FTY720 is effective in inhibiting MM growth and this mechanism is, at least in part, mediated by re-activation of PP2A tumor suppression function via SET inhibitor displacement and suppression of SphK1 activity." (PMID 28298211, 2017). "To assess exclusively the effect of the SET protein in the process, we selected the non-tumour cell line HEK293 overexpressing it." (PMID 28460463, 2017). "In present study, we investigated the oncogenic role of SET by SET-knockdown and showed that SET silencing impaired cell growth rate, colony formation and tumor sphere formation in A549 cells." (PMID 26575017, 2016). "Intriguingly, there is a growing body of literature demonstrating the anti-tumor effects of antagonizing SET-mediated PP2A inhibition." (PMID 26575017, 2016). "Consistent with previous reports about the effects of PP2A activation in other tumor models, knockdown of SET decreased phosphorylation of the PP2A targets AKT and ERK1/2 without affecting their expression levels." (PMID 25945834, 2015). "In our cohort with SET knockdown, we only observed a single tumor formation at 96 days post implantation." (PMID 26563471, 2015). "In the present study, we found that SET expression was significantly increased in NSCLC cells and tissues, and was closely associated with tumor progression and poor prognosis." (PMID 25945834, 2015). "We found that high expression of SET was correlated with advanced tumor stages and regional lymph node metastasis." (PMID 25945834, 2015). "Immunohistochemistry (IHC) analysis confirmed SET protein knockdown in the HN12shSET xenograft tumor cells." (PMID 24555657, 2014). "The results of the present study also identified that SET expression (at the mRNA level) in 31 patients was markedly increased in 70.9% of tumor specimens compared with adjacent normal tissues." (PMID 24944693, 2014).
tumor (continued). "Data showed that I2PP2A/SET is overexpressed in 70% (7/10, n = 10) of these tumours, whereas C18-ceramide and CerS1 mRNA levels are decreased (∼50%) in the majority of tumours (8/10, n = 10) compared to non-cancerous lung tissues (respectively)." (PMID 23180565, 2013). "Expression of WT-I2PP2A/SET in A549/sh-I2PP2A/SET cells restored tumour suppressor effects of FTY720." (PMID 23180565, 2013). "It is likely that SET inhibits the transcription of many miRNAs, perhaps including tumor suppressors such as let-7, while silencing of SET removes this block." (PMID 23335963, 2013). "We show here that the tumour suppressor ceramide binds I2PP2A/SET selectively in the nucleus and including its K209 and Y122 residues as determined by molecular modelling/simulations and site-directed mutagenesis." (PMID 23180565, 2013). "SET was found to be overexpressed in 50–60% of BC tumor samples and BC cell lines." (PMID 37834160, 2023). "The SET nuclear proto-oncogene is known to be upregulated in TNBC tumor samples with CIP2A." (PMID 37681908, 2023). "Furthermore, SET, a universally famous tumour suppressor, is an oncoprotein that decreases PP2A activity." (PMID 35593206, 2022). "Therefore, it is worth further examining which components in hypoxic tumor supernatant can promote the nucleocytoplasmic shuttling of SET in macrophages to regulate chemotaxis." (PMID 36224346, 2022). "Next, we focused on the impact of SET knockout on the TAM phenotype within the tumor." (PMID 36224346, 2022). "SET was overexpressed in about 50–60%, and CIP2A in about 90%, of breast cancers, and CIP2A overexpression was associated with triple negative, basal, and claudin-low tumor subtypes." (PMID 30341686, 2018). "Given our demonstration that GnRH decreases SET protein expression in pituitary gonadotrope cells, one could hypothesize that GnRH anti-tumor effect could be driven at least in part by an inhibition of SET expression." (PMID 30052687, 2018). "SET protein levels in tumor tissues were normalized with paired normal tissues as 100%." (PMID 28655918, 2017). "Furthermore, we found that SET KD inhibited in vivo tumor growth of CIP-m cells in the xenograft model." (PMID 28655918, 2017). "SET is a multifunctional protein that is overexpressed in human neoplasms." (PMID 24944693, 2014). "Interestingly, reconstitution of WT-I2PP2A/SET expression in A549/sh-I2PP2A/SET cells increased growth of tumours ∼50% compared to controls." (PMID 23180565, 2013). "Importantly, at least 4 of 10 patients exhibited overexpression of I2PP2A/SET in combination with down-regulation of C18-ceramide in their lung tumours, suggesting that tumour suppressive ceramide/PP2A signalling is altered in these tumours." (PMID 23180565, 2013). "Overall, these data suggest that targeting I2PP2A/SET might be a novel therapeutic strategy for the treatment of NSCLC to reactivate PP2A tumour suppressor signalling." (PMID 23180565, 2013). "In addition to its activity as an inhibitor of PP2A, SET is also a potent inhibitor of the tumour suppressor NM23-H1." (PMID 16953242, 2006). "In addition, knocking-down SET expression decreases tumor cell sensitivity to TGI1002." (PMID 25900240, 2015). "The primary tumor samples displayed higher expression of both ZBTB11 and SET than the adjacent tissues." (PMID 38355937, 2024). "There is evidence that the knockdown of these inhibitors restored the tumor suppressor function of PP2A, and NB cells treated with SET or CIP2A siRNA had a decreased malignant phenotype." (PMID 39594793, 2024). "In this study, we observed that PDL1, PD1, SOD2, PARP, SET, TGF-ß, NF-kB, and BCL2 were highly expressed in the control tumor tissue." (PMID 38258094, 2024). "Targeting and disrupting SET/PP2A interaction would result in a recovered PP2A activity and consequently reduced tumor growth." (PMID 37111665, 2023). "We have previously preclinically validated a tumor-penetrating and interfering peptide that blocks PP2/SET interaction against CLL." (PMID 37111665, 2023).
tumor (continued). "Taken together, these results suggest that hypoxic tumor supernatant activates PKC by phosphorylation and promotes the nuclear export of SET, which subsequently regulates ERK and P38 activation." (PMID 36224346, 2022). "The SET inhibitor OP449 effectively decreased the viability of NB cells, independent of their molecular alterations and in line with a tumor suppressor function of PPP2CA." (PMID 35814385, 2022). "Since FTY720 binds SET, leading to PP2A reactivation, the SET–FTY720 complex was studied using NMR spectroscopy, which revealed that FTY720 binding disrupts SET dimerization, allowing for a specific PP2A trimer activation with tumor suppressive activities." (PMID 35565311, 2022). "As a consequence, FTY720 sequesters SET, which is released from the catalytic subunit of PP2A, leading to PP2A reactivation and tumour suppression." (PMID 36345878, 2022). "Taken together, our data suggest that SET deletion in macrophages impairs the activation of ERK and P38 signaling induced by hypoxic tumor supernatant and thus blocks the chemotaxis of macrophages toward hypoxic supernatant." (PMID 36224346, 2022). "Collectively, all of these observations indicate that lncRNA-HGBC functions to sequester miR-502-3p then to activate SET and AKT downstream pathway, thus rendering tumor cells highly aggressive." (PMID 31752906, 2019). "Therefore, SET protein may play a role in interstitial cells to promote/suppress tumor progression." (PMID 31557212, 2019). "In this study, we found that phosphatase activity by PP2A was strongly repressed in this tumor; that is, the PPP2R1A expression was suppressed and that expression of SET, a PP2A suppressor, was upregulated by PAX3-FOXO1 in ARMS." (PMID 29861864, 2018). "Ser/Thr protein phosphatase 2A (PP2A) plays a critical role as a tumor suppressor, and SET/I2PP2A, the endogenous inhibitory protein of PP2A, binds directly to PP2A and suppresses its phosphatase activity." (PMID 28655918, 2017). "Altogether, our results show that miR-199b is a tumor suppressor whose downregulation independently determines worse outcome and emerges as a potential contributing mechanism to inhibit PP2A via SET overexpression in a subgroup of mCRC patients." (PMID 27517624, 2017). "To understand the clinical impacts on targeting SET/PP2A/p-Akt signaling in NSCLC patients, we examined the expression of p-Akt and explored it relationship with SET expression in tumor tissues." (PMID 26575017, 2016). "In this report, we validated the high prevalence and tumor-specificity of SET expression in NSCLC, and demonstrated the closely correlated expressions of SET and p-Akt." (PMID 26575017, 2016). "To confirm the clinical relevance of SET protein in NSLCL, we first analyzed the presence of SET in the tumor tissue obtained from 53 patients with NSCLC and the adjacent normal parts of lung in 43 patients of this cohort." (PMID 26575017, 2016). "Future studies will address the relative tumor initiating capacities of PP2A and its known regulators, inhibitor of PP2A (CIP2A) and SET (I2PP2A) both alone and in concert, using similar reconstitution assays." (PMID 26563471, 2015). "To ascertain that the binding of TGI1002 to SET is responsible for the anti-tumor activity of TGI1002 in vivo, we analyzed the interaction of SET with PP2A in tumor tissues from the xenografted mice." (PMID 25900240, 2015). "Recent data provided a unique mechanism for ceramide-mediated PP2A activation, revealing that ceramide directly binds SET, relieving PP2A from SET, increasing PP2A activity, leading to tumor suppression, consistent with anti-proliferative roles of ceramide." (PMID 25642418, 2014). "The data show that FTY720 or shRNA-mediated knockdown of I2PP2A/SET, both of which decreased tumour growth, increased serum LDH in mice." (PMID 23180565, 2013).
tumor (continued). "Accordingly, while molecular targeting of I2PP2A/SET by stable knockdown prevented further tumour suppression by FTY720, reconstitution of WT-I2PP2A/SET expression restored this process." (PMID 23180565, 2013). "Overall, these data suggest that direct targeting of I2PP2A/SET by FTY720 induces PP2A/RIPK1-dependent necroptosis through its kinase domain, leading to cell death and subsequent tumour suppression." (PMID 23180565, 2013). "Because FTY720 directly bound I2PP2A/SET, we explored its ability to inhibit tumour growth via activation of PP2A tumour suppressor signalling." (PMID 23180565, 2013). "Taken together, our data indicate PRRG2 as a direct target of ZBTB11, which contributes to ZBTB11-, but not SET-, mediated regulation of tumor metastasis." (PMID 38355937, 2024). "Treatment with a SET inhibitor, OP449, significantly reduces xenografted tumor cell proliferation." (PMID 37097392, 2023). "The inhibitory activity of PP2A by overexpression of SET and CIP2A increases hyper-phosphorylated proteins, including pS62-MYC and pAkt, and induces proinflammatory cytokines TNF-α and IL-1, which are presented as essential molecules in tumor promotion." (PMID 37097392, 2023). "The motif was fused with a CPP to synthesise a chimeric protein, which was shown to be effective in inhibiting tumour progression, indicating that it could block the interaction between PP2A and SET." (PMID 35593206, 2022). "Taken together, our data suggest that SET is not functionally related to either the recruitment of monocytes or the differentiation of monocytes into macrophages within the tumor." (PMID 36224346, 2022). "Collectively, our data suggest that SET deletion in macrophages releases the activity of PP2A, which subsequently inhibits the activation of ERK and P38 signaling induced by hypoxic tumor supernatant, resulting in the blockade of macrophage migration toward hypoxic tumor supernatant." (PMID 36224346, 2022). "However, activation of PPP2CA by the SET inhibitor OP449 also led to growth inhibition of the cells, in line with a tumor suppressor function of PPP2CA." (PMID 35814385, 2022). "Immunohistochemistry confirmed the reduction in SET protein levels in tumours developed in the siSET-treated group: H-scores of tumours were 187.5 ± 52.0 for non-treated group, 198.3 ± 45.8 for siControl, and 66.7 ± 39.8 for siSET group, P < 0.05." (PMID 34244560, 2021). "Moreover, we examined SET mRNA expression in 38 pairs NSCLC tissues and found that SET expression was significantly elevated in tumor samples." (PMID 34774019, 2021). "The SET protein, also known as I2PP2A or template activating factor-1 (TAF-1), is another oncogenic cellular inhibitor of PP2A by direct binding to PP2AC (the catalytic subunit) and plays a role in modulating tumor progression and metastasis." (PMID 30154367, 2018). "Moreover, the SET antagonists OP449 and FTY720 induced down-regulation of set gene expression, and thus reduced tumor growth." (PMID 30341686, 2018). "The previous study identified that Rac1 could binding to SET, also known as TAF1β (template activating factor 1β), and suppress the function of PP2A by increasing the phosphorylation level in tumor cells." (PMID 28057023, 2017). "Because the anti-tumor effects of FTY720 depend on PP2A activation, the PP2A-independent function of SET may be responsible for this contradiction." (PMID 28655918, 2017). "Moreover, we found that ectopic expression of SET induces resistance in NSCLC cells to paclitaxel, and, importantly, antagonizing SET via siRNA or a novel SET inhibitor, EMQA, significantly enhances the in vitro and in vivo anti-tumor effects of paclitaxel." (PMID 26575017, 2016).